Y_RNA (Y RNA )
Gene: Miscellaneous RNA gene on chromosome X (107,901,145 to 107,901,246, reverse strand). Ensembl gene ENSG00000207363.
Homologues: Orthologues: chimpanzee Y_RNA (98% identical), macaque Y_RNA (95% identical). Paralogues in human: Y_RNA (90% identical), RNY3 (89% identical), Y_RNA (88% identical), Y_RNA (87% identical), RNY3P1 (86% identical), Y_RNA (86% identical), Y_RNA (85% identical), Y_RNA (84% identical), RNY3P14 (83% identical), RNY3P16 (83% identical), Y_RNA (83% identical), RNY3P13 (82% identical), and 96 more.